GRM4 (glutamate metabotropic receptor 4)
Diseases named in the same sentence as GRM4 in open-access papers (continued):
Sharing a sentence is not in itself a finding about the gene and the disease.
tumor (19 papers, 2018 to 2026). "The activation of cAMP by mGluR4 knockout in the tumor was associated with the increase in antitumor immune response played by CD8+ T and NK cells, with the increased levels of pCREB and IFNGR1 in Grm4−/− CD8+ T cells." (PMID 36817470, 2023). "In BC high expression of GRM4 was associated with better prognosis in patients and furthermore may act as a tumour suppressor." (PMID 39127986, 2024). "Perturbations of GRM4 strengthened the anti-tumor immunity by activating NK, CD4(+) T, and CD8(+) T cells." (PMID 37215113, 2023). "GRM4 functions as a tumor suppressor that inhibits cancer cell proliferation, migration and invasion." (PMID 31492116, 2019). "GRM4 was highly expressed in tumour, late‐stage, and high‐grade tissues (P ≤ 0.003), and a high expression of GRM4 was associated with poor OS (P < 0.001)." (PMID 30488581, 2018). "Additionally, we found that more than 50% of tumor cells expressed GRM4 in half of the GRM4-positive patients, and 37.34% of patients were GRM4-positive among which 80% of tumor cells expressed GRM4." (PMID 41573636, 2025). "In some patients, GRM4 was expressed in the cytoplasm of tumor cells." (PMID 41573636, 2025). "GRM4 exhibited tumor-specific membrane/cytoplasmic expression in 80.38% of BC patients (127/158) across all subtypes (≥70% positivity), with 51.27% showing >50% tumor cell positivity." (PMID 41573636, 2025). "In the magnified image, the expression of GRM4 on the tumor cell membrane was observable." (PMID 41573636, 2025). "Additionally, GEPIA database analysis revealed that GRM4 was expressed at low levels in 291 adjacent normal tissues but was highly expressed in 1085 tumor tissues, with a significantly higher expression in tumor tissues compared to adjacent normal tissues." (PMID 41573636, 2025). "Metabotropic glutamate receptor 4(GRM4) plays a novel role in suppressing anti-tumor immunity." (PMID 37215113, 2023). "Additionally, we found that more than 50% of tumor cells expressed GRM4 in half of BC patients." (PMID 41573636, 2025). "Our results suggested miR-328-3 inhibited the expression of GRM4, a tumor suppressor in MCF7 luminal BC cells and overexpression of miR-328-3p promoted proliferation, migration and invasion in GRM4 stably expressing cells, indicating that miR-328-3p may switch to an oncogene in the context of GRM4." (PMID 31492116, 2019). "In our patient samples, IHC staining showed that GRM4 was expressed in 80.38% (127/158) of patients, whereas 19.62% (31/158) samples had little or no expression of GRM4 in the tumor cells." (PMID 41573636, 2025). "Grm4-/- mice significantly suppressed B16F10, 3LL, and MC38 tumor growth." (PMID 36817470, 2023).
cancer (9 papers, 2014 to 2025). A tumor composed of atypical neoplastic, often pleomorphic cells that invade other tissues. "IHC analysis revealed that protein expression of GRM4 was significantly higher in BC samples than that in paired non-carcinoma tissues (P = 0.0003)." (PMID 31492116, 2019). "On the other hand, Bin Xiao reported that GRM4 may inhibit cancer cell proliferation, migration, and invasion." (PMID 41573636, 2025). "In our study, we found that GRM4 expression is related to the clinical stage, with cancer at an advanced stage, GRM4 expression may increase, so we hypothesize that GRM4 may promote cancer cell development." (PMID 41573636, 2025). "Research on the roles of GRM4 in cancers remains scarce and contentious." (PMID 41573636, 2025). "Our study is the first to report that GRM4 expression was significantly higher in patients over 40 years old, and it may be an age-related gene playing an important role in cancer development." (PMID 41573636, 2025). "GRM4 was a negative regulator of antitumor immunity and targeting of GRM4 might represent a novel strategy to improve cancer immunotherapy." (PMID 36798123, 2023). "GRM4 was reported to be involved in adaptive immunity reactions in cancers." (PMID 31492116, 2019). "Previous studies have demonstrated that GRM4 may have different functions in various cancers." (PMID 33318294, 2020). "There were four mRNAs not only upregulated in ESCC compared with para-cancer tissues but also in Fu-High compared with Fu-Low: C-Type Lectin Domain Family 12 Member A (CLEC12A), Glutamate Metabotropic Receptor 4 (GRM4), Protein Arginine Methyltransferase 8 (PRMT8), and Peptide YY 2 (PYY2)." (PMID 39471360, 2025).
psychiatric disorder (3 papers, 2018 to 2022). A disorder characterized by behavioral and/or psychological abnormalities, often accompanied by physical symptoms. "The disease-gene association scores for Grm4, filtered for psychiatric disorders that share the impulsivity domain." (PMID 34982027, 2022).
neurodegenerative disease (2 papers, 2018 to 2025). A disorder of the central nervous system characterized by gradual and progressive loss of neural tissue and neurologic function. "In general, metabotropic glutamate receptors, such as the one encoded by GRM4, have been proposed as drug targets for neurodegenerative diseases to address pathological alterations in glutamatergic signaling." (PMID 39737748, 2025).
infection (1 paper, 2018). The state of being infected such as from the introduction of a foreign agent such as serum, vaccine, antigenic substance or organism. "The RT-qPCR analysis showed that the level of miR-29b-3p dramatically increased after the AAV-miR-29b-3p infection to 4.42 times that in the AAV-GFP group, while GRM4 expression decreased by 56.1%." (PMID 30369596, 2018). "The GRM4 protein levels in the rat PFC were also detected by Western blotting and showed a significant decrease after the AAV-miR-29b-3p infection." (PMID 30369596, 2018).
GRM4 also shares sentences with these, for which no sentence is quoted: Parkinson disease (10 papers); bladder cancer (4); Dyskinesia (3); glioma (3); clear cell renal cell carcinoma (2); ischemia (2); lung carcinoma (2); multiple sclerosis (2); anxiety disorder (1); atrial fibrillation (1); Autoimmunity (1); brain injury (1); breast tumors (1); cholangiocarcinoma (1); Chorea (1); CNS tumors (1); colon adenocarcinoma (1); colorectal adenocarcinoma (1); coronary artery disease (1); Diamond-Blackfan anemia (1); Dystonia (1); fragile X syndrome (1); generalized epilepsy (1); gout (1); heart failure (1); hepatocellular carcinoma (1); invasive breast carcinoma (1); ischemic stroke (1); KBG syndrome (1); lung adenocarcinoma (1).
A further 17 diseases each share a sentence with GRM4 in 1 paper.